APOE (apolipoprotein E)
Diseases named in the same sentence as APOE in open-access papers (continued):
Sharing a sentence is not in itself a finding about the gene and the disease.
hypertriglyceridemia (86 papers, 2007 to 2025). A laboratory test result indicating elevated triglyceride concentration in the blood. "APOE-induced hypertriglyceridemia has been linked to its carboxyl-terminal region (amino acids 260–270), particularly residues L261, W264, F265, L268, and V269." (PMID 41354325, 2025). "A recent study also shows that high levels of both apoE and apoA2 were strongly inversely associated with the ability of lipoprotein lipase to hydrolyze TG in plasma—the process which plays a key role in hypertriglyceridemia development." (PMID 35745122, 2022). "Previous studies have shown that apolipoprotein E (ApoE) gene polymorphism plays a role in the development of gout, primary hyperuricemia, and hypertriglyceridemia." (PMID 36620636, 2022). "APOE has been previously associated to gout and hyperuricemia as a potential link with hypertriglyceridemia, a common finding in patients with gout." (PMID 34321071, 2021). "The severe hypertriglyceridemia manifested independently of apoE, as it also occurred in APOE deficient mice." (PMID 31779116, 2019). "The patient was found to have the e3/ e4 isoform of ApoE, increasing risk of hypertriglyceridemia in DKA." (PMID 29988659, 2018). "Adenovirus-mediated gene transfer studies in mice revealed that apoE region 1–202 associated with lipoproteins efficient in the clearance of lipoprotein remnants, while region 203–299 induced hypertriglyceridemia." (PMID 28660014, 2017). "Further studies showed that the triple substitution with alanine of Leu261, Trp264, and Phe265 residues in apoE2 or apoE4 promoted the formation of spherical HDL particles and prevented the hypertriglyceridemia in apoE- and apoAI-deficient mice." (PMID 28660014, 2017). "Since systemic overexpression of apoE in mice causes hypertriglyceridemia, novel anti-atherosclerotic therapies which specifically target apoE expression in certain cell types are urgently needed." (PMID 28355284, 2017). "It has been noted that the ApoE gene polymorphism plays a role in the development of gout, primary hyperuricemia, and hypertriglyceridemia." (PMID 25890021, 2015). "In heterozygotes, the mutation was associated with mild to moderate hypertriglyceridemia, and very likely with type 3 hyperlipoproteinemia in a subject who was also homozygous for APOE E2/E2." (PMID 17883852, 2007). "Although the mechanisms causing hypertriglyceridemia are not fully understood, certain genetic mutations, such as Apolipoprotein E mutations, APOA5 mutation, and APOC2 mutation, may be involved, leading to protein defects and function loss." (PMID 39267857, 2024). "In addition, pediatric patients with malignant lymphoma and acute lymphoblastic leukemia who express isoforms E3 and E4 of APOE are at higher risk of developing extreme hypertriglyceridemia." (PMID 36873459, 2022). "Physiological plasma APOE levels facilitate clearance of atherogenic lipoproteins; however, supraphysiological levels induce hypertriglyceridemia and impair cholesterol clearance." (PMID 41354325, 2025). "Though physiological levels of wild-type APOE promote atherogenic lipoprotein clearance, overexpression has been shown to result in severe hypertriglyceridemia." (PMID 41354325, 2025). "This includes low or absent levels of HDL in the plasma, elevated serum free cholesterol, hypertriglyceridemia, the presence of lipoprotein X, reduced levels of apolipoprotein A-II and A-II, and increased levels of apolipoprotein E." (PMID 39114211, 2024). "The most common clinical features were edema (95.3%), hematuria (88.1%), hypertriglyceridemia (88.1%), and increased serum apoE levels (89.7%)." (PMID 34513758, 2021).
hypertriglyceridemia (continued). "ApoC-II mimetics reverse hypertriglyceridemia and ApoE-based peptides such as Ac-hE18A-NH2 reduce cholesterol and triglyceride (TG) levels in humans." (PMID 34441867, 2021). "The most common clinical features were edema, hematuria, hypertriglyceridemia, and increased serum apoE levels." (PMID 34513758, 2021). "We therefore examined the data of a previously published randomized double-blind placebo-controlled dose-ranging phase 2 study of the effects of volanesorsen in patients with hypertriglyceridemia according to the distribution of APOE isoforms among patients." (PMID 31092690, 2019). "We analyzed the impact of APOE genotype in hypertriglyceridemia patients from a previous study testing the efficacy of ASO-mediated APOC-III lowering with volanesorsen in relation to apoE isoforms." (PMID 31092690, 2019). "Even the subtlest increase of plasma APOE concentration from physiological (2–5 mg/dL), triggers severe hypertriglyceridemia that is due to direct inhibition of plasma LPL activity and increased hepatic VLDL production." (PMID 29770778, 2017). "Regarding apoE involvement in lipid metabolism, site-specific mutated or truncated apoE gave valuable clues on various regions and residues of apoE responsible for hypertriglyceridemia and athero-genesis/protection." (PMID 28660014, 2017). "We showed previously that APOE-induced hypertriglyceridemia requires the carboxyterminal domain 260-299 of APOE, and specifically helix 8 that extends from aminoacids 260-270." (PMID 29770778, 2017). "Too much apoE stimulates very low-density lipoproteins production in the liver and impairs lipoprotein lipase-mediated lipolysis, leading to hypertriglyceridemia." (PMID 25852220, 2015). "Affected patients typically present with nephrotic syndrome, hypertriglyceridemia and elevated plasma apoE levels." (PMID 23448537, 2013). "While we are the first to demonstrate this effect in hamsters, other investigators have previously shown that the overexpression of apoE can also induce hypertriglyceridaemia." (PMID 18070363, 2007). "In an apoE knockout mouse for example, severe hypertriglyceridaemia similar to our phenotype, was seen when these mice were fed a high fat fish oil diet." (PMID 18070363, 2007). "Notably, Imamura described two cases of psoriasis patients with hypertriglyceridemia and demonstrated a reduction in ApoC3 and ApoE levels following clofibrate treatment." (PMID 40137160, 2025). "LPG is characterized by elevated serum ApoE and hypertriglyceridemia." (PMID 33663537, 2021). "Nephrotic-range proteinuria, hypertriglyceridemia, and progressive renal dysfunction accompanied by elevated ApoE level are common among most patients, and half of the patients may eventually develop uremia in 1–27 years." (PMID 33663537, 2021). "APOE was identified to be essential for TG-modulating, and three genes APOA1, APOA2, and APOE were reported to be associated with hypertriglyceridemia, which may increase the risk of acute pancreatitis." (PMID 31467879, 2019). "ApoE plays an important role in the normal metabolism of TG-rich lipoproteins: too much ApoE causes hypertriglyceridemia by impairing lipolysis and stimulating hepatic VLDL TG production, and too little ApoE impairs plasma clearance of TG-rich lipoproteins and their remnants." (PMID 29390290, 2017). "Further research is required to determine whether or not a compensatory increase in hepatic Sdc1 expression can prevent the hypertriglyceridemia in ApoE-/- mice." (PMID 29151984, 2017).
hypertriglyceridemia (continued). "The specific modulation in macrophages is important since it promotes peripheral apoE expression, avoiding the increased levels of systemic apoE provided by the hepatocytes, which may lead to hypertriglyceridemia." (PMID 28355284, 2017). "On the other hand, upregulation of APOE may lead to hypertriglyceridemia through stimulating the production of VLDL triglyceride in the liver and impairing the LPL-mediated lipolysis." (PMID 27781209, 2016). "We have previously shown that the low apoE levels may contribute to hypertriglyceridemia in residents of the European North of Russia." (PMID 25852220, 2015). "The main outcome was the significant association between hypertriglyceridemia and sleep disorders in the cross-sectional analysis at baseline, even after adjusting for age, sex, racial profile, educational level, GDS total score, APOE ε4, cognition-related main diagnosis, and BMI." (PMID 39342373, 2024). "Inhibition of the apoE-mediated hepatic uptake of VLDL is not the sole mechanism accounting for the hypertriglyceridemic effect of apoC1 overexpression since apoC1 transgenic mice also develop hypertriglyceridemia in an apoE-deficient context." (PMID 36471375, 2022). "Absence of polygenic hypertriglyceridemia in our patient, based on the risk scores calculated, may be interpreted as an emphasis on the importance of his APOE genotype for clinical manifestation." (PMID 33537346, 2020). "However, APOE ε2 is not entirely benign—it is linked to hypertriglyceridemia and type III hyperlipoproteinemia, which may increase cardiovascular risk in susceptible individuals." (PMID 40149595, 2025). "However, in hypertriglyceridemia, LPL’s activity is reduced to fewer than five pools per day, resulting in partially delipidated TRL with longer half-life and greater atherogenic potential due to defective hydrolysis perhaps associated to an apoE/apoCIII imbalance." (PMID 40943205, 2025). "Multiple regression analysis indicated that low LPL, high ApoC2, high ApoC3, high ApoE, and high ANGPTL8 levels were the determinants of fasting hypertriglyceridemia." (PMID 34293055, 2021). "ApoE is an exchangeable apolipoprotein found in TG-rich lipoproteins and HDL, which plays many important functions crucial for normal lipoprotein metabolism, but it was also found that its accumulation is related to hypertriglyceridemia." (PMID 35745122, 2022). "In this study, we evaluated the effects of saringosterol in atherosclerotic ApoE−/− mice and no side effects of hepatic triglyceride accumulation and hypertriglyceridaemia were found." (PMID 34564147, 2021). "We conclude that volanesorsen lowers plasma TG and increases HDL-C levels in a human hypertriglyceridemia patient cohort independent of the APOE genotype." (PMID 31092690, 2019). "Altogether, our study shows for the first time that the apoE genotype in hypertriglyceridemia patients does not negatively affect the efficiency of volanesorsen to lower plasma TGs." (PMID 31092690, 2019). "Our proposed metabolic switch model has clinical relevance, as apoC-III ASO administration in a clinical study lowered plasma TG levels in hypertriglyceridemia patients independent of the expressed APOE isoform." (PMID 31092690, 2019). "Conversely, the APOE level in VLDL particles increased with progression of renal dysfunction, which may lead to their delayed metabolism and, in a consequence, to hypertriglyceridemia since APOE inhibits lipoprotein lipase activity." (PMID 30851738, 2019). "Over time of study hypertriglyceridemia and hyperuremia developed in all groups irrespective of drink treatment likely as a result of the aging process which is typically accelerated in ApoE-/- mice." (PMID 23547749, 2013).
hypertriglyceridemia (continued). "Moreover, our data suggest that knockout of ApoE in female non-agouti KKAy–/– genotypes may trigger a state of hypertriglyceridemia in these animals." (PMID 36505365, 2022).
memory impairment (82 papers, 2006 to 2026). "ApoE-deficient mice exhibit fewer huddled contacts during sleep, reduced motor activity in novel environments, and learning and memory impairments." (PMID 40026711, 2025). "It has also been reported that 12-month-old ApoE-deficient mice exhibit memory impairment in the passive avoidance test." (PMID 40026711, 2025). "A previous study reported that 12-month-old ApoE-deficient mice show decreased cognitive function in the Y-maze test and memory impairment in the passive avoidance test." (PMID 37396111, 2023). "A previous study reported the upregulation of apolipoprotein-E (ApoE) in the hippocampi of MeHg-exposed animals with memory impairments, which is often associated with AD and has also been investigated in populations exposed to mercury." (PMID 36136496, 2022). "We tested the efficacy of CVD therapeutics as treatment for memory impairment associated with the increased cardiovascular burden in aged ApoE-/- mice (i.e., increased plasma cholesterol and higher-than-normal BP)." (PMID 34349106, 2021). "APOE-ε4 carrier status was associated with greater memory impairment in analyses that co-varied for duration of disease." (PMID 33658917, 2021). "In each study, higher proportions of people with isolated substantial relative memory impairment had ≥1 APOE ε4 allele than any other subgroup (overall p = 1.5 × 10−27)." (PMID 30514930, 2020). "Overall, the proportion of people with ≥ 1 APOE ε4 allele was 15% higher in those with isolated substantial memory impairment (65%) compared with the entire sample (50%)." (PMID 30514930, 2020). "We previously showed in ACT that more people with isolated substantial relative memory impairment had at least one APOE ε4 allele than people in other subgroups." (PMID 30514930, 2020). "Conversely, we showed that homozygosity for ABCA7 rs3764650T allele shows a protective effect against memory impairment in AD patients that carry APOE-ε4, and TT-carriers had higher functional connectivity within the vDMN in ε4+ carriers." (PMID 31831047, 2019). "In demented populations, females tend to have greater memory impairment than males, possibly as a result of APOE-ε4 allele presence (i.e., possession of at least one APOE-ε4 allele), and faster whole brain and temporal lobe atrophic rates." (PMID 29857518, 2018). "The apolipoprotein E (APOE) ε4 allele associates with memory impairment in neurodegenerative diseases." (PMID 28948085, 2017). "Previous studies demonstrated that AD patients with APOE ε4 had poorer cognitive function, particularly the significantly severe memory impairment, which was possibly because APOE ε4 was associated with temporal lobe atrophy (especially hippocampus) and dysfunction in the default mode network." (PMID 37697966, 2024). "Two genes are consistently associated with all seven memory scores: neuron navigator 2 (NAV2) and Translocase Of Outer Mitochondrial Membrane 40 Homolog (TOMM40), where TOMM40 is proximal to APOE and has been reported to be associated with the memory impairment." (PMID 25859259, 2015). "Demographically, women are over-represented in limbic predominant AD and APOE ε4, related to greater structural atrophy and memory impairment within the cluster." (PMID 41301726, 2025). "As memory impairment represents an early symptom of AD, researchers are increasingly interested in the link between memory impairment and the APOE ε4 function." (PMID 35884866, 2022). "We published APOE results from ACT; the proportion of those with isolated substantial memory impairment with ≥ 1 APOE ε4 allele was 12% higher than overall in that study." (PMID 30514930, 2020). "In aged apolipoprotein E4 knockin (apoE4-KI) mice—a model of the major genetic risk factor for AD—we find that reduced SWR abundance and associated CA3 SG power predicted spatial memory impairments measured 1–2 months later." (PMID 31747587, 2019).